DAPK2 (death associated protein kinase 2)
Diseases named in the same sentence as DAPK2 in open-access papers (continued):
Sharing a sentence is not in itself a finding about the gene and the disease.
morbid obesity (1 paper, 2024). An excess of body weight, normally defined as an individual with a body mass index greater than 35 or a body weight greater than one hundred percent of ideal body weight. "The mechanism of autophagy attenuation was shown to be dependent on death-associated protein kinase 2 (DAPK2), reported to be one of the most downregulated genes in the AT transcriptome in human morbid obesity." (PMID 38971910, 2024).
myeloma (1 paper, 2021). "In tumors such as B-lymphoma and myeloma, silencing of DAPK2 methylation is associated with poor tumor prognosis." (PMID 34093817, 2021).
osteoporosis (1 paper, 2026). A condition of reduced bone mass, with decreased cortical thickness and a decrease in the number and size of the trabeculae of cancellous bone (but normal chemical composition), resulting in increased fracture incidence. "In summary, we delineate a melatonin/YTHDF3/DAPK2 protective axis that safeguards against unloading‐induced bone deterioration via post‐transcriptional regulation of Dapk2, thereby unveiling new mechanistic perspectives and therapeutic opportunities for disuse osteoporosis." (PMID 42149012, 2026).
osteosarcoma (1 paper, 2023). A usually aggressive malignant bone-forming mesenchymal neoplasm, predominantly affecting adolescents and young adults. "The activation of E2F1 in osteosarcoma cells increased endogenous DAPK2 in parallel with cell death." (PMID 36827114, 2023).
ovarian carcinoma (1 paper, 2016). A malignant neoplasm originating from the surface ovarian epithelium. "Whether the effect of miR-520g on DAPK2 is specific or all the members of miR-520 family have the same effect of DAPK2 in ovarian cancer is worth to be further explored." (PMID 27049921, 2016).
renal fibrosis (1 paper, 2014). A final common manifestation of a wide variety of chronic kidney diseases characterized by glomerulosclerosis and tubulointerstitial fibrosis. "Dapk2 null mice are phenotypically normal under steady state conditions, but display some resistance to extracellular matrix deposition in experimental renal fibrosis indicating that DAPK2 plays a profibrotic role in kidney injury." (PMID 24906443, 2014).
tumor (24 papers, 2012 to 2025). "DAPK2 encodes a member of the serine/threonine protein kinase family, which functions as a tumor suppressor and regulates autophagic and apoptotic processes in various cell types." (PMID 36033519, 2022). "As a member of the Ca2+/calmodulin-regulated serine/threonine kinases family, death-associated protein kinase 2 (DAPK2) is a tumor suppressor that affects various cellular activities, including cellular immune function and cell death." (PMID 36559016, 2022). "Unsurprisingly, the putative tumor suppressor gene death associated protein kinase 2 (DAPK2) was predicted to greatly contribute to tumor regression at the LUAD tumor stage 1–2 interface." (PMID 34940617, 2021). "Next, the same authors showed that AND treatment increased DAPK2 (Death-Associated Protein Kinase 2), a calcium- and calmodulin-dependent regulator of apoptosis and tumor suppressor, and TNSFR11B expression." (PMID 27171110, 2016). "Finally, we confirmed that DAPK2 overexpression can inhibit tumor growth and metastasis, but the underlying mechanism needs further study." (PMID 38779664, 2024). "DAPK2, (death‐associated protein kinase 2), a Ca2+/calmodulin‐regulated serine/threonine kinase, has been characterized as a critical regulator of apoptosis, autophagy, and inflammation and a tumor suppressor." (PMID 35611939, 2022). "In the case of lung cancer, there is a connection between lower levels of DAPK2 expression and heightened tumor proliferation, along with an unfavorable prognosis." (PMID 39971705, 2025). "In this study, we discovered that the expression of DAPK2 is lower in patients with T1-3 tumors than in patients with T4 tumors, suggesting that the expression of DAPK2 is related to the local tumor progression and metastasis." (PMID 38779664, 2024). "The anoikis-related gene DAPK2 was shown to inhibit tumor growth and metastasis through the AKT1/CyclinD1 pathway, presenting a new target for the treating of CRC." (PMID 38779664, 2024). "We conducted additional experiments to confirm the tumor suppressor role of DAPK2 both in vitro and in vivo." (PMID 38779664, 2024). "Previous reports indicated that the treatment of tumor cells with cacalol promote the expression of DAPK2 and caspase-3." (PMID 39329902, 2024). "Ultimately, the role of the anoikis-regulatjng gene DAPK2 in suppressing tumor growth and metastasis was confirmed both in vitro and vivo." (PMID 38779664, 2024). "The cell-derived xenograft model demonstrated that the tumor volume in DAPK2 overexpression group was significantly smaller compared to the control group." (PMID 38779664, 2024). "DAPK2, a known tumor-suppressor, mediates both the anti-proliferative and the pro-apoptotic effects of miR-1285 depletion." (PMID 36836704, 2023). "As a whole, the predictions made by sPLS-DA aligned well with the associated survivability for each tested gene, especially at early LUAD stage-stage interfaces, such as the LUAD tumor stage 1–2 interface, which includes DAPK2 and PLAC9." (PMID 34940617, 2021). "In particular, survivorship analysis of early LUAD tumor regression candidates at the stage 1–2 interface (e.g., DAPK2 and PLAC9) revealed these genes to serve as positive LUAD prognosis markers." (PMID 34940617, 2021). "Further evidence corroborating a tumor-suppressive role of DAPK2 comes from hematological malignancies, where its stable over-expression enhances all-trans retinoic acid (ATRA)-induced granulocytic differentiation of leukemic cell lines." (PMID 32244500, 2020). "We show that DAPK2, a known tumor-suppressor, is a novel miR-1285 target and mediates both the anti-proliferative and the pro-apoptotic effects of miR-1285 depletion." (PMID 32244500, 2020). "We compared the protein levels of DAPK2 in miR-520g overexpressing or downregulated cell lines using western blotting, and in tumor xenografts by IHC staining." (PMID 27049921, 2016).
tumor (continued). "We screened proliferation, cell cycle and tumor invasion-related targets whose 3′UTRs included the miR-520g-specific binding site, and identified DAPK2 as a candidate for further study." (PMID 27049921, 2016). "In the same study, restoring DAPK2 expression abolished miR-520 h-mediated tumor promotion and drug resistance." (PMID 27049921, 2016). "Although it shows significant structural differences from DAPK1, the founding member of this protein family, DAPK2 is also thought to be a putative tumour suppressor." (PMID 25741596, 2015). "Thus, further investigation of DAPK2 is vital for understanding tumor biology and exploring new therapeutic strategies." (PMID 39971705, 2025). "Tumoral samples showed a 5.24‐fold reduction in DAPK2 expression (p = 0.011)." (PMID 39971705, 2025). "The nude mice xenograft tumor model confirmed that high expression of DAPK2 inhibited tumor growth." (PMID 38779664, 2024). "The expression of DAPK2 was negatively correlated with T stage of the tumor." (PMID 38779664, 2024). "DAPK2 was substantially downregulated in the tumor samples compared to the paracancerous group." (PMID 38779664, 2024). "Finally, DAPK2-overexpressing plasmid was transfected to measure its effect on tumor proliferation and metastasis in vitro and in vivo." (PMID 38779664, 2024). "Notably, 8 autophagy-related genes (CAPN10, DAPK2, MBTPS2, ST13, CFLAR, FADD, PEX14 and TSC2) and 2 immune cells (Mast cells and Eosinophils) were revealed to be highly associated with tumor prognosis." (PMID 34093817, 2021). "At present, DAPK2 has been found to act as a tumor suppressor in several types of leukemia." (PMID 34422899, 2021). "The third top SNP (rs12908891; P = 1.39E-06) is located DAPK2 on chromosome 15 that belongs to a family of related serine/threonine kinases shown to be involved in multiple functions, including apoptosis, autophagy, tumor suppression, and inflammation." (PMID 30361487, 2021). "Interestingly, DAPK2 was predominantly found in the hematopoietic compartment and emerged as a tumor suppressor in several types of leukemia." (PMID 30287790, 2018). "DAPK2 is regarded as a tumor suppressor in non-solid tumors and is implicated in apoptotic cell death." (PMID 30287790, 2018). "Studies exploring the selective reconstitution of DAPk2 catalytic activity were first to demonstrate the proof-of-concept strategy of restoring tumor suppressive kinase activity by targeted delivery of actively constituted DAPk in the context of an immunokinase fusion protein." (PMID 28976934, 2017). "This study suggests that miR-520g contributes to tumor progression and drug resistance by post-transcriptionally downregulating DAPK2, and that miR-520g may be a valuable therapeutic target in patients with EOC." (PMID 27049921, 2016). "In vitro assays showed that DAPK2 inhibited tumor cell proliferation, wound healing and invasion." (PMID 27049921, 2016). "DAPK2 is a tumor suppressor that promotes apoptosis and tumor cell death." (PMID 27049921, 2016). "This may be a mechanism by which, depending on the intracellular context, DAPK2 can act as a tumour suppressor gene." (PMID 25741596, 2015). "Interestingly, of the few genes that, via sPLS-DA, were predicted to contribute to tumor regression at certain stage-to-stage interfaces—including DAPK2, PLAC9, ABCB9, MELTF, CTHRC1, and OCIAD2, testing for LUAD patient survivability via AK4 combination resulted in a negative prognosis." (PMID 34940617, 2021). "However, long-term in vivo studies could aid in gauging the potential ability of tumor cells to develop other escape mechanisms, as DAPk2 may also be regulated by oligomerization through their C-terminal tail (Tail) sequences." (PMID 28976934, 2017). "However, whether miR-520g induces tumor progression and chemoresistance by directly downreguating DAPK2 in EOC is unclear." (PMID 27049921, 2016). "The expression of DAPK2 and LOC101928988 was downregulated in tumor tissues compared to the control group." (PMID 39971705, 2025).
tumor (continued). "Our results revealed that the expression of DAPK2 and LOC101928988 was downregulated in tumoral tissues compared to that in the control group." (PMID 39971705, 2025). "To validate DAPK2 as a prognostic indicator for CRC, we investigated the tumor-suppressive properties of DAPK2 in CRC." (PMID 38779664, 2024). "We found that miR-520g overexpression or knockdown induced significant downregulation or upregulation of DAPK2 protein levels, respectively, in both EOC cell lines and tumor xenografts." (PMID 27049921, 2016). "Upregulation of anti-apoptotic genes, including BAG1, BCL11B and SERPINB2, and downregulation of apoptotic genes, such as DAPK2, HRK and TP53INP1, can promote tumor cell survival." (PMID 23024765, 2012). "The significant positive correlation between DAPK2 and LOC101928988 expression levels suggests that these genes may interact in regulatory pathways critical for tumor development, which could be a therapeutic target." (PMID 39971705, 2025). "In contrast to DAPK1 and DAPK3, DAPK2 has not been identified as a tumor suppressor in solid tumors." (PMID 30287790, 2018). "In contrast to DAPK1, DAPK2 has not been identified as a tumor suppressor in solid tumors." (PMID 34422899, 2021). "Although it is thought to be a tumour suppressor in haematological malignancies, DAPK2, in contrast to other DAPK family proteins, has not been identified as a tumour suppressor in solid tumours." (PMID 33809172, 2021). "Expression of an immunokinase consisting of the transmembrane glycoprotein receptor of CD30 (CD30L) fused with a CaM negative DAPk2 mutant demonstrated apoptosis inducing capabilities in CD30 positive and DAPk2-negative tumor cell lines (L540 and L1236)." (PMID 28976934, 2017).
cancer (21 papers, 2012 to 2025). A tumor composed of atypical neoplastic, often pleomorphic cells that invade other tissues. "Death-associated protein kinase 2 (DAPK2) regulates cytoskeleton-associated proteins to suppress cancer cells directed migration." (PMID 31552190, 2019). "Increased expressions of pro-apoptotic genes BNIP3, tumor necrosis factor related apoptosis-inducing ligand (TRAIL), and death-associated protein kinase 2 (DAPK2) have been reported to contribute to apoptosis induction in ceramide accumulation in cancer cells." (PMID 29546056, 2018). "The loss of DAPk1 and DAPk2 expression in multiple types of human cancer ignited the profound interest in the kinase family regarding their function and involvement in various diseases." (PMID 28976934, 2017). "In addition, inactivation of the DAPK2 gene has been associated with cancer development." (PMID 33809172, 2021). "Despite its established roles, the potential of DAPK2 as a therapeutic target in cancer treatment remains an active area of research, underscoring the complexity of its function in cellular processes." (PMID 39971705, 2025). "Understanding the functions of DAPK2 is essential, as it reveals not only its roles in autophagy and cytoskeletal regulation but also its significant implications in cancer biology." (PMID 39971705, 2025). "The expression of DAPK2 was also reported to be regulated by non-coding RNAs in cancers and other diseases." (PMID 34422899, 2021). "This has led to the development of DAPk1 and DAPk2 based fusion proteins for the treatment of cancer." (PMID 28976934, 2017). "As miR-520 h and miR-520g both are the member of the miR-520 family, and they can both down regulate DAPK2 expression in cancer." (PMID 27049921, 2016). "Using two genetically distinct cancer cell lines as models, we have identified a new role for DAPK2 in the regulation of mitochondrial integrity." (PMID 25741596, 2015). "It has been reported that DAPK2 exhibits proapoptotic functions in cancer cells." (PMID 36827114, 2023). "DAPK2 is involved in regulating oxidative stress in cancer cells via MAPK pathway." (PMID 35611939, 2022). "It was found that miR‐520h interferes with DAPK2 expression post‐transcriptionally by directly binding to the 3′‐UTR of DAPK2 mRNA, thereby protecting cancer cells from apoptosis." (PMID 39971705, 2025). "Eighteen overlapping DEGs were identified between the two CRC cell lines, four of which are closely related to cancer progression, namely FGF1, THBS2, DAPK2, and GSTM2." (PMID 41039172, 2025). "Previous studies showed that DAPK family members, including DAPK1, DAPK2 and DAPK3 play a crucial regulatory role in malignant tumor development, in terms of cell apoptosis, proliferation, invasion and metastasis." (PMID 34422899, 2021). "When comparing RM with PC, we identified key regeneration-related genes APOD and IBSP, along with several significant pathways: cAMP signaling pathway (HHIP), cytokine-cytokine receptor interaction (IL17D), pathways in cancer (HHIP, DAPK2), and biosynthesis of cofactors (RDH12, HAAO)." (PMID 39684926, 2024). "Most genes from the “Pathways in cancer” (FLT3, IGF1R, DAPK2, PLD1 and MMP9) are inhibited due to the action of BE resulting in an anti-proliferative and pro-apoptotic action of the combined therapy, with the notable exception of the up-regulation of the apoptosis inhibitor BIRC3." (PMID 28359318, 2017). "Other studies indicate that the regulatory functions of individual C19MC miRNAs in cancer are related to silencing the expression of factors and signaling pathways related to adhesion, migration, differentiation, growth and angiogenesis (Rap1b, ABCG2, DAPK2, ephrins-EphB2 and EphB4, CXCR4)." (PMID 36430313, 2022).
cardiovascular diseases (1 paper, 2023). "As an upstream regulator of DAPK2, miR‐22‐3p does not only interact with noncoding RNA in a variety of cardiovascular diseases but also plays an important role in the development of DCM." (PMID 37735821, 2023).
kidney disease (1 paper, 2014). "Tubulointerstitial fibrosis in experimental CKD arises directly from resident interstitial cells, and we therefore evaluated the expression of DAPK2 in the expanded interstitium of mice with kidney disease induced by chronic cisplatin administration." (PMID 24906443, 2014).
neurodevelopmental disorder (1 paper, 2025). A behavioral and cognitive disorder with onset during the developmental period that involves impaired or aberrant development of intellectual, motor, or social functions. "MIABEPIR modulates BBB integrity and endothelial autophagy through the Dapk2 pathway, highlighting a potential therapeutic target for neurodevelopmental disorders." (PMID 40000424, 2025).
DAPK2 also shares sentences with these, for which no sentence is quoted: anaplastic thyroid carcinoma (1 paper); atrial fibrillation (1); Breast Tumors (1); cardiomyopathy (1); Cerebral ischemia (1); colorectal tumors (1); endometrial cancer (1); glioma (1); heart failure (1); immune disorder (1); lymph node metastasis (1); myocardial infarction (1); Parkinson disease (1); pulmonary hypertension (1); vitiligo (1).